BRCA1 (BRCA1 DNA repair associated)
Diseases named in the same sentence as BRCA1 in open-access papers (continued):
Sharing a sentence is not in itself a finding about the gene and the disease.
Hereditary breast and ovarian cancer syndrome (continued). "Patient 16 was diagnosed with Hereditary Breast and Ovarian Cancer syndrome due to a heterozygous PV in BRCA1 (NM_007294.4: c." (PMID 40936482, 2025). "For Latin American populations, while BRCA1 and BRCA2 PVs are well-known in hereditary breast and ovarian cancer syndrome (HBOC), other HCS associated with risks for cancers beyond breast and ovarian are less well-characterized." (PMID 40065011, 2025). "As HBOC syndrome follows an autosomal dominant inheritance trait, first-degree relatives of BRCA1/2 carriers have a 50% chance of sharing a familial pathogenic variant (PV) irrespective of sex." (PMID 40596937, 2025). "Germline pathogenic variants of HR-related genes, such as BRCA1 and BRCA2 (BRCA1/2), cause hereditary breast and ovarian cancer syndrome (HBOC)." (PMID 40224668, 2025). "The most common cause of hereditary breast and ovarian cancer (HBOC) is the pathogenic variants in the BRCA1 and BRCA2 (BRCA1/2) genes." (PMID 39240499, 2024). "Germline alteration of HR-related genes, such as BRCA1 and BRCA2, causes hereditary breast and ovarian cancer (HBOC)." (PMID 38589490, 2024). "PACC exhibits a higher frequency of BRCA1/2 mutations compared to PDAC and is more likely to be an associated cancer of hereditary breast and ovarian cancer syndrome (HBOC)." (PMID 39188100, 2024). "PGV prevalence was assessed for 682 BRs of 281 probands with BRCA1/BRCA2 wild-type hereditary breast and ovarian cancer (HBOC) syndrome." (PMID 39003386, 2024). "FA is an inherited bone marrow failure syndrome caused by defects in any one of so far identified 22 FANC genes including hereditary breast and ovarian cancer (HBOC) genes BRCA1 and BRCA2." (PMID 36345163, 2023). "This involves variants in the genes BRCA1 (n = 1; FAM215) and BRCA2 (n = 2; FAM91; FAM209), which are associated with an increased risk of hereditary breast and ovarian cancer (HBOC)." (PMID 37274821, 2023). "The most frequently covered health condition of interest was BRCA1/BRCA2 genetic testing (n = 19) for hereditary breast and ovarian cancer (HBOC)." (PMID 37531363, 2023). "In patients with hereditary breast and ovarian cancer (HBOC) syndrome, who are heterozygously mutated in either BRCA1 or BRCA2, cancer‐initiating cells mostly undergo loss of wild‐type BRCA1/2 allele." (PMID 36345163, 2023). "Hereditary breast and ovarian cancer (HBOC) can be caused by alterations in several genes, among which the tumour suppressors Breast cancer susceptibility gene 1 and 2 (BRCA1 and BRCA2) are the most prevalent and studied." (PMID 34981296, 2022). "Pathogenic germline mutations in the BRCA1 and BRCA2 (BRCA1/2) genes contribute to hereditary breast/ovarian cancer (OC) in White/mestizo Colombian women." (PMID 35641219, 2022). "Germline mutations consistent with hereditary breast and ovarian cancer syndrome (HBOC), in BRCA1 and BRCA2, were found in four patients." (PMID 36359225, 2022). "PVs in BRCA1 and BRCA2 are classically associated with hereditary breast and ovarian cancer syndromes." (PMID 36232851, 2022). "The German Consortium for Hereditary Breast and Ovarian Cancer (GC-HBOC) conducted a comprehensive BRCA screening and revealed a higher mutation frequency in BRCA1 than that in BRCA2." (PMID 36232564, 2022). "Germline pathogenic mutations of BRCA1 and BRCA2 suppress the HR mechanism and cause hereditary breast and ovarian cancer (HBOC) syndrome." (PMID 35785170, 2022). "BRCA1- and BRCA2-associated Hereditary Breast and Ovarian Cancer Syndrome (HBOC) increases the relative and absolute risk of developing breast and ovarian cancer and, to a lesser extent, prostate and pancreatic cancer." (PMID 35395021, 2022).
Hereditary breast and ovarian cancer syndrome (continued). "The most common contributors to hereditary BC are BRCA1 and BRCA2, which are associated with hereditary breast and ovarian cancer (HBOC)." (PMID 35806485, 2022). "The representative genes involved in HR are BRCA1 and BRCA2, whose deleterious variants are associated with hereditary breast and ovarian cancer (HBOC) syndrome." (PMID 35008774, 2021). "Two BRCA1 founder mutations (c.5266dupC, and c.4035delA) account for approximately 80% of all detectable BRCA1 and BRCA2 mutations in breast-ovarian cancer families." (PMID 33478551, 2021). "BRCA1 and BRCA2 are considered major cancer predisposing genes as they account for a significant proportion of HBC and HBOC syndrome families in all studied populations." (PMID 34298626, 2021). "A representative hereditary tumor due to germline deficiency of HR, which is represented by alterations in BRCA1 or BRCA2 (BRCA1/2), is the hereditary breast and ovarian cancer (HBOC) syndrome." (PMID 35008774, 2021). "The nuclease MRE11A is often included in genetic test panels for hereditary breast and ovarian cancer (HBOC) due to its BRCA1-related molecular function in the DNA repair pathway." (PMID 33510186, 2021). "BRCA1 and BRCA2 mutations in women of different ethnicities undergoing testing for hereditary breast-ovarian cancer." (PMID 35096615, 2021). "Recently, Evans and colleagues reported the first case of germline BRCA1 methylation in two families affected by Hereditary Breast and Ovarian Cancer Syndrome." (PMID 32276467, 2020). "In this study, we screened 95 samples of patients with HBOC syndrome clinical suspicion, using a multi-gene panel sequencing both flanking and coding regions of BRCA1, BRCA2 and another 19 DNA repair genes." (PMID 32039725, 2020). "Germline mutations in the BRCA1 and BRCA2 genes cause hereditary breast and ovarian cancer syndrome (HBOC)." (PMID 32468491, 2020). "Approximately 25% of women diagnosed with tubo-ovarian high-grade serous carcinoma have germline deleterious mutations in BRCA1 or BRCA2, characteristic of hereditary breast and ovarian cancer syndrome, while somatic mutations have been detected in 3–7%." (PMID 33233347, 2020). "A total of 95 individuals with HBOC syndrome clinical suspicion in Southeast Brazil were sequenced, and 25 samples were evaluated for insertions/deletions in BRCA1/BRCA2 genes." (PMID 32039725, 2020). "It is well-known that the inherited mutations of BRCA1 and BRCA2 genes resulted in hereditary breast and ovarian cancer syndrome (HBOC)." (PMID 32821249, 2020). "The characterization of germline pathogenic variants in the BRCA1 and BRCA2 genes are relevant for prevention setting and for the clinical management of hereditary breast and ovarian cancer (HBOC)." (PMID 33287145, 2020). "BRCA1- and BRCA2-associated hereditary breast and ovarian cancer syndromes are among the best-known and most extensively studied hereditary cancer syndromes." (PMID 32733558, 2020). "In conclusion, we detected a significantly high prevalence of PALB2, BARD1, and BLM mutations, with a low frequency of mutant CHEK2 in the current Japanese cohort of 568 patients with BRCA1/2 WT HBOC syndrome." (PMID 32566746, 2020). "Of the 205 students who wrote about HBOC syndrome, 56% argued for BRCA1/2 testing before adulthood, citing reasons such as prevention and life planning." (PMID 32414353, 2020). "BRCA1 (MIM# 113705) is one of two large genes (BRCA1 and BRCA2) most frequently mutated in families with hereditary breast and ovarian cancer syndrome (HBOC)." (PMID 31683985, 2019). "Genetic testing for BRCA1/2 genes is widely used as a strategy to reduce incidence and morbidity of hereditary breast and ovarian cancer (HBOC)." (PMID 31771539, 2019). "Inherited pathogenic variants in BRCA1 and BRCA2 are the most common causes of hereditary breast and ovarian cancer (HBOC)." (PMID 31395037, 2019).
Hereditary breast and ovarian cancer syndrome (continued). "Heterozygous germline mutations in BRCA1 and BRCA2 are responsible for the majority of hereditary breast and ovarian cancer (HBOC) syndrome patients." (PMID 31921645, 2019). "In patients with suspected HBOC syndrome, 30 (5%) were identified as carriers of the 9–12 del BRCA1." (PMID 31545835, 2019). "The aim of this study was to identify genomic alterations in BRCA1/BRCA2 wild-type tumor samples from women with family history strongly suggestive of hereditary breast/ovarian cancer." (PMID 29938003, 2018). "Hereditary breast and ovarian cancer syndrome (HBOC) is an inherited genetic disease, of which BRCA1 and BRCA2 gene mutations are a prevalent cause." (PMID 29487695, 2018). "Hereditary breast and ovarian cancer syndrome (HBOC), associated with BRCA1/2, illustrates an interesting difference in the OWG and AWG approaches." (PMID 30011878, 2018). "BRCA1 and BRCA2 (collectively named BRCA hereafter) are the main genes causing hereditary breast and ovarian cancer syndrome (HBOC), and are also associated with an increased risk of prostate and pancreatic cancers." (PMID 29161300, 2017). "Hereditary breast and ovarian cancer is a cancer predisposition syndrome that results from inherited—that is, germline—loss-of-function mutations in BRCA1 or BRCA2 genes, collectively, BRCA1/2." (PMID 28782058, 2017). "Heterozygous BRCA1 and BRCA2 mutations underlying hereditary breast and ovarian cancers (HBOCs) have also been reported to be involved in cellular radiosensitivity and cancer susceptibility." (PMID 28729543, 2017). "Until recently, the molecular diagnosis of hereditary breast and ovarian cancer (HBOC) was mostly based on BRCA1/2 testing." (PMID 27779110, 2017). "Germline mutations in BRCA1 and BRCA2 genes (BRCA1/2) predispose to hereditary breast and ovarian cancer syndrome (HBOC), and their dysregulation increases the risk of cancers." (PMID 29383094, 2017). "Germline pathogenic variants in BRCA1 and BRCA2 (BRCA) are the main cause of Hereditary Breast and Ovarian Cancer syndrome (HBOC)." (PMID 29161300, 2017). "Today, genetic testing for Hereditary Breast Ovarian Cancer syndrome has moved from testing of the BRCA1 and BRCA2 genes to broader panel testing." (PMID 28281021, 2017). "Germline mutations in the high penetrance BRCA1 and BRCA2 (BRCA1/2) genes, responsible for the Hereditary Breast and Ovarian Cancer syndrome (HBOC), account for 20–30% of these cases." (PMID 28199346, 2017). "BRCA1 and BRCA2 mutations explain approximately one-fifth of the inherited susceptibility in high-risk Finnish hereditary breast and ovarian cancer (HBOC) families." (PMID 28738860, 2017). "Next-generation sequencing (NGS) has enabled new approaches for detection of mutations in the BRCA1 and BRCA2 genes responsible for hereditary breast and ovarian cancer (HBOC)." (PMID 27793035, 2016). "Most hereditary breast and ovarian cancer (HBOC) is attributable to a combination of family history and BRCA1 and BRCA2 (BRCA1/2) mutations, with the latter conferring a 40%–75% lifetime disease risk." (PMID 27417623, 2016). "In the 1990s, linkage analyses and positional cloning in breast and breast-ovarian cancer families led to the identification of BRCA1 and BRCA2." (PMID 25848941, 2015). "Specific germline mutations in the hereditary breast-ovarian cancer susceptibility (HBC/HBOC) genes, BRCA1, BRCA2 and PALB2, have been shown to recur in French Canadians of Quebec, Canada, and this has been attributed to common ancestors." (PMID 25925845, 2015). "Mutations in BRCA1 and BRCA2 are responsible for a large proportion of breast-ovarian cancer families." (PMID 23704879, 2013). "All patients had been selected for BRCA1/2 testing by virtue of having an early-onset of disease or a family history suggestive of hereditary breast/ovarian cancer." (PMID 23806170, 2013).
Hereditary breast and ovarian cancer syndrome (continued). "In 1996, the US-based biotechnology company Myriad Genetics began offering genetic diagnostic tests for mutations in the genes BRCA1 and BRCA2, which are linked to hereditary breast and ovarian cancer." (PMID 23885284, 2013). "Germline inactivating mutations in BRCA1 and BRCA2 genes are responsible for Hereditary Breast and Ovarian Cancer Syndrome (HBOCS)." (PMID 23613828, 2013). "Genetic counseling and testing for BRCA1 and BRCA2 gene mutation has become an integral part of high-risk patient evaluation and management for hereditary breast ovarian cancer." (PMID 22382806, 2012). "Our findings indicate that both BRCA1 and BRCA2 mutations account for a substantial proportion of hereditary breast/ovarian cancer in the Southern Chinese population." (PMID 22970155, 2012). "A typical example is provided by the case of Ashkenazi Jews, where three founder mutations: BRCA1 c.66_67delAG BRCA1 c.5263insC, and BRCA2 c.5946delT account for most of familial breast-ovarian cancer." (PMID 23961350, 2012). "Germ-line mutations in the BRCA1 and BRCA2 genes are major contributors to hereditary breast/ovarian cancer." (PMID 21939546, 2011). "Mutations of BRCA1 and BRCA2, common in hereditary breast and ovarian cancer (HBOC) syndrome, predispose carriers to developing breast, ovarian, and a variety of other cancers including PC." (PMID 22312493, 2011). "Stratification of families according to number of breast-ovarian cancer cases showed that BRCA1/2 positivity was significantly higher in families with 3 or more affected members than those with only two cases, with frequencies of 11.7% and 3.5%, respectively." (PMID 19619314, 2009). "Germline mutations in the susceptibility genes BRCA1 and BRCA2 in hereditary breast/ovarian cancer, though low in prevalence, are highly penetrant and show geographical variations." (PMID 18662409, 2008). "The medical files of BRCA1 or BRCA2 mutation carriers and members of a hereditary breast/ovarian cancer (HBOC) family, who had undergone prophylactic surgery, were reviewed." (PMID 15083174, 2004). "This study indicates a BRCA2 contribution of 10% (95% CI 2.5–17.5) to our original cohort of 59 breast-ovarian cancer families, whereas the contribution of BRCA1 had been estimated at 46% (95% CI 33–59)." (PMID 11207042, 2001). "Pathogenic germline variants in the BRCA1 and BRCA2 genes predispose individuals to HBOC syndrome." (PMID 39980563, 2025). "BRCA1/2 genes are responsible for hereditary breast and ovarian cancer (HBOC) syndrome." (PMID 37956396, 2024). "Currently, there is no clear boundary between FA-S and BRCA1-associated hereditary breast and ovarian cancer (HBOC), as exemplified by PN2-3 and P8." (PMID 38146508, 2023). "Detection of pathogenic variants with varying penetrance in the BRCA1 and BRCA2 genes are responsible for approximately two-thirds of hereditary breast and ovarian cancer, with cumulative risks ranging from 16–84% and 11–87% for BRCA2 and BRCA1, respectively, by age 80 years." (PMID 36568162, 2022). "BRCA1 and BRCA2 are associated with hereditary breast and ovarian cancer syndrome (HBOC)." (PMID 34476650, 2021). "Similarly, while heterozygous FANCS/BRCA1 mutations are associated with hereditary breast and ovarian cancer syndromes, biallelic loss of FANCS/BRCA1 is associated with FA development." (PMID 34830134, 2021). "As shown in an early targeted analysis of 20 variants in FCs, 84% of BRCA1 and BRCA2 positive HBC and HBOC syndrome families harbour one of five specific PVs in these genes accounting for the high frequency of these PVs observed in BC- and OC-affected individuals in this population." (PMID 34298626, 2021).
Hereditary breast and ovarian cancer syndrome (continued). "In this study, we report the frequencies of germline variants in previously recognized causal genes for HBOC syndrome across 568 Japanese patients with wildtype (i.e., mutation-negative) BRCA1/2 genes and a strong family history." (PMID 32566746, 2020). "BRCA1- and BRCA2-associated hereditary breast and ovarian cancer syndrome (HBOC) is characterized by an increased susceptibility to breast and ovarian cancer, and to a lesser extent certain other cancers, especially in individuals with a BRCA2 germline mutation." (PMID 32468491, 2020). "In this regard, the aim of this study was to identify chromosomal and subchromosomal copy number alterations in tumor samples from Brazilian women without BRCA1/BRCA2 germline mutations with family history strongly suggestive of HBOC syndrome." (PMID 29938003, 2018). "Here, we report the characterization of the BRCA1 c.190T>C (p.Cys64Arg) mutation, mapped to the RING-finger domain coding region, that we detected in 43 hereditary breast/ovarian cancer (HBOC) families, for the large part originating from the province of Bergamo (Northern Italy)." (PMID 24516540, 2014). "The spectrum of BRCA1/2 genetic variation in breast-ovarian cancer patients has been scarcely investigated outside Europe and North America, with few reports for South America, where Amerindian founder effects and recent multiracial immigration are predicted to result in high genetic diversity." (PMID 23961350, 2012). "We examined seven cases from breast-ovarian cancer families with tumours that showed BRCA1-like pathology but did not have detectable BRCA1 or BRCA2 germline mutations present." (PMID 18269736, 2008). "For example, identification of a somatic pathogenic variant in the BRCA1 or BRCA2 genes following tumor profiling may lead to personalized treatment with a PARP inhibitor, but it may also be indicative of Hereditary Breast and Ovarian Cancer syndrome if present in the germline." (PMID 39238026, 2024). "However, it is now estimated that more than one-half of individuals with a pathogenic variant (PV) who meet the National Comprehensive Cancer Network (NCCN) testing criteria for hereditary breast and ovarian cancer (HBOC) carry PVs in genes other than BRCA1 or BRCA240." (PMID 38017116, 2023). "Furthermore, BRCA1 mutations were strongly associated with hormone-receptor negative status in previous analyses of high-risk breast-ovarian cancer families whereas most BRCA2-mutated tumours do not have a TNBC phenotype." (PMID 23110154, 2012). "BRCA1 and BRCA2 with other homologous recombination genes are the most tested genes in hereditary breast and ovarian cancer (HBOC) patients." (PMID 36171877, 2022). "In attempt of gaining more information regarding the molecular profile of BRCA1/2 in HBOC, we conducted a study in which we analyze their molecular profile on selected Moroccan patients suspected of having HBOC syndrome." (PMID 32778078, 2020). "In the mid-1990s, BRCA1 and BRCA2 which are part of the DNA-repair machinery were identified to play a crucial role in hereditary breast and ovarian cancer (HBOC)." (PMID 31395037, 2019). "Different laboratories have implemented NGS to analyze BRCA1 and BRCA2 or panels of candidate genes suspected as being involved in Hereditary Breast Ovarian Cancer (HBOC)." (PMID 27793035, 2016). "However, not all breast and breast-ovarian cancer families carry a mutation in BRCA1 or BRCA2." (PMID 25848941, 2015).